MTDH (metadherin)
Diseases named in the same sentence as MTDH in open-access papers (continued):
Sharing a sentence is not in itself a finding about the gene and the disease.
tumor (continued). "MTDH is transmembrane protein that contributes to the growth, metastasis, drug resistance and relapse of tumor." (PMID 34277708, 2021). "MTDH is also involved in major malignant behaviors of tumor cells including in promoting tumor metastasis, invasion, angiogenesis, tumor cell proliferation, and growth." (PMID 34552061, 2021). "The expressions of MTDH in xenograft tumours derived from KYSE30/CDDP-R cells with sh-NORAD were lower than those cells with sh-NC." (PMID 34893064, 2021). "Dysregulated tumor-infiltrating immune cells and inhibitory immune checkpoint expression were correlated with MTDH expression." (PMID 34622157, 2021). "Here, we systematically investigated the expression of MTDH, deconvoluted tumor immune environments, and estimated gene signatures in the The Cancer Genome Atlas (TCGA) pan-cancer, independent cancer series, and multiple cancer immunotherapy cohorts." (PMID 34622157, 2021). "MTDH promotes multiple hall markers of aggressive cancer behaviors, including tumor proliferating, metastasis, angiogenesis, and chemotherapy resistance, by activating MAPK, PI3K/AKT, and WNT/β-catenin pathways in diverse cancers." (PMID 34622157, 2021). "Similar to the previous results, the expression of MTDH was higher in tumor specimens than in normal tissues, with a positive signal detected in almost 60% of patients." (PMID 32993809, 2020). "The abnormal expression and dysfunction of MTDH are related to the viability, survival, and metastasis of tumor cells." (PMID 32952599, 2020). "Many previous studies illustrated that MTDH can enhance tumor progression and metastasis through activating several classic cancer-promoting signaling pathways, such as epithelial-mesenchymal transition (EMT) and the NF-κB and MAPK signaling pathways." (PMID 31978894, 2020). "What is more, MTDH has been demonstrated to function vitally in tumor genesis, development, and resistance to chemotherapy." (PMID 32952599, 2020). "Other studies have revealed that MTDH plays an important regulatory role in tumor proliferation, differentiation, apoptosis, migration, invasion, and drug resistance via the Ha-ras, PI3K/Akt, NF-kappa B, and Wnt/beta-catenin signaling pathways." (PMID 33312941, 2020). "Intensive efforts have been made to reveal the essential function of MTDH in promoting tumor progression." (PMID 32968053, 2020). "Studies have shown that MTDH plays an important role in tumour progression by mediating unlimited cell growth, apoptosis avoidance, cell migration and invasion, angiogenesis and drug resistance." (PMID 32251289, 2020). "Among these potential targets, MTDH was firstly concerned because of its special functions in tumor progression and its sequence feature of mRNA 3′-UTR." (PMID 32968053, 2020). "Many studies have revealed that metadherin (MTDH) is highly expressed in a variety of malignant solid tumours and plays an important role in the occurrence and development of tumours." (PMID 32251289, 2020). "A significant reduction in tumor metastasis in the MTDH knockdown group compared with the control group was identified." (PMID 31978894, 2020). "More recently, studies have highlighted the role of metadherin (MTDH) in stimulating tumor progression, metastasis, and drug resistance in various cancers." (PMID 30791936, 2019). "MTDH/AEG-1 promotes cell survival, inhibits apoptosis, and promotes tumor progression via multiple PI3K/Akt pathways." (PMID 31131259, 2019). "To confirm the role of MTDH knockdown in the interference of tumor growth, we sectioned tumors and analyzed the levels of MTDH protein." (PMID 30227879, 2018). "The tumor in the MCF-7–MTDH–shRNA group was dramatically smaller than MCF-7–MTDH group as well as both controls, confirming that the knockdown of MTDH enhanced cell sensitivity to TAX exposure." (PMID 30227879, 2018).
tumor (continued). "To achieve in vivo therapeutic assessment by tumor-specific knockdown of MTDH, we have devised a polymer-based nanocarrier to co-deliver anti-MTDH siRNA and TAX into tumor tissues." (PMID 30227879, 2018). "Metadherin (MTDH), also known as LYRIC, AEG-1, or 3D3, has been expressed in multiple tumor types as an oncogene and associated with aberrant proliferation and drug resistance of tumor cells." (PMID 30227879, 2018). "We further examined the effect of MTDH expression on in vivo MCF-7 tumor cell growth and TAX treatment efficiency using a mouse xenograft model." (PMID 30227879, 2018). "For in vivo therapeutic study, we employed targeted nanocarriers to specifically co-deliver anti-MTDH small interfering RNA (siRNA) (for tumor-specific silence of MTDH gene) and TAX drug." (PMID 30227879, 2018). "Further functional investigations revealed that MTDH also mediates tumor progression, proliferation, angiogenesis, invasiveness, and metastasis." (PMID 29029495, 2017). "Microscopic examination of PCNA-stained tumor sections shows a decrease in PCNA-positive cells in AED-1/MTDH siRNA-treated rats as compared with the untreated controls." (PMID 26909607, 2016). "MTDH has been proposed to promote tumor progression through the integration of multiple signaling pathways including ras, myc, Wnt, PI3K/AKT, and NF-κB in various types of cancer." (PMID 27755556, 2016). "Odds ratios (ORs) and hazard ratios (HRs) were used to demonstrate the impact of MTDH on tumor metastasis and prognosis respectively." (PMID 27917902, 2016). "Further knockdown of MTDH expression by shRNA in MM cells induced cell apoptosis, inhibited MM cells growth in vitro and decreased xenograft tumor formation in vivo." (PMID 26683226, 2016). "Various literatures have demonstrated that overexpression of Metadherin (MTDH) is correlated with tumor metastasis and it can predict poor survival outcomes in female reproduction malignancies." (PMID 27917902, 2016). "Untreated control rats exhibit a median tumor volume of 383.92 mm3 ± 68.79, whereas AED-1/MTDH siRNA-1 and AED-1/MTDH siRNA-2-treated rats reveal tumor volumes of 184.27 mm3 ± 57.16, 159.47 mm3 ± 50.60." (PMID 26909607, 2016). "Both pooled results showed that MTDH in female reproduction cancers can be regarded as an unfavorable predictor in tumor metastasis." (PMID 27917902, 2016). "MVD, VEGF and MTDH are factors related to angiogenesis, which play a vital role in tumor growth and progression." (PMID 26109910, 2015). "MTDH is not only overexpressed in numerous types of cancer, but is also involved in tumor metastasis." (PMID 25684730, 2015). "All these results indicated that MTDH protein levels in most HCC tissues are higher than non-tumor tissues, and knockdown of MTDH inhibited growth and induced apoptosis in HCC cells through the activation of PTEN." (PMID 26287185, 2015). "High MTDH expression in HCC is positively correlated with tumor microvascular invasion, tumor grade and stage, and high recurrence rate." (PMID 26287185, 2015). "We found that MTDH mRNA expression in HCC tissues was higher compared to adjacent matched non-tumor tissues." (PMID 26287185, 2015). "We found that MTDH protein levels are higher in most HCC cancerous tissues compared with their matched adjacent non-tumor tissues." (PMID 26287185, 2015). "A recent study showed that MTDH played a critical role in mammary tumorigenesis by regulating oncogene-induced expansion and activities of tumor-initiating cells (TICs) through interacting with SND1." (PMID 25333261, 2014). "The results indicated that miR-302c suppresses EndMT of ECs through inhibiting MTDH expression and thus attenuates MTDH's contribution to tumor growth." (PMID 25027009, 2014). "Overexpression of AEG-1/MTDH synergizes with oncogenic Ha-Ras to enhance the soft agar colony formation of non-tumorigenic immortalized melanocytes and provides evidence of the tumor promoting activity of AEG-1/MTDH." (PMID 25009642, 2014).
tumor (continued). "Adenoviral delivery of AEG-1/MTDH-targeting shRNA inhibits xenograft primary tumor growth in HCC mice." (PMID 25009642, 2014). "To determine the clinical significance of MTDH in HGSOC, we examined the correlation between MTDH expression in HGSOC tumor samples and the clinical outcome (n=76)." (PMID 25333261, 2014). "In conclusion, this study demonstrates that EC-specific miR-302c suppresses tumor growth in HCC through MTDH-mediated inhibition of EndMT." (PMID 25027009, 2014). "Studies have established that AEG-1/MTDH is crucial in tumor progression, including transformation, the evasion of apoptosis, invasion, angiogenesis and metastasis." (PMID 25009642, 2014). "In summary, AEG-1/MTDH overexpression markedly correlates with advanced tumor characteristics and a poor clinical prognosis, and is a promising target for novel therapeutics." (PMID 25009642, 2014). "In summary, AEG-1/MTDH is crucial in lymph node metastasis and contributes to tumor progression, including transformation, the evasion of apoptosis, invasion and metastasis." (PMID 25009642, 2014). "In HBV-related HCC patients, AEG-1/MTDH is a potential prognostic marker for overall survival (OS) and tumor progression, and is a chemotherapeutic target." (PMID 25009642, 2014). "ECs isolated from tumor tissues expressed significantly lower levels of miR-302c and VE-cadherin, but a higher level of MTDH, β-catenin, FSP1 and α-SMA than ECs isolated from normal liver tissues." (PMID 25027009, 2014). "In HCC tumors, the high expression of AEG-1/MTDH has also been found to correlate with microvascular invasion, pathological satellites, poor differentiation and tumor-node-metastasis (TNM) stages II to III." (PMID 25009642, 2014). "MTDH promotes tumor progression by modulating multiple oncogenic signaling pathways, such as NF-κB, PI3K/Akt and Wnt/β-catenin pathways." (PMID 22768080, 2012). "MTDH(metadherin), an important oncogene that is widely overexpressed in various cancers, is a potential biomarker of tumor malignancy." (PMID 23240043, 2012). "MTDH plays a critical role in tumor biology, and it is involved in a variety of tumor biological behaviors." (PMID 23240043, 2012). "The other most commonly expressed adhesion molecule, metadherin (MTDH), is expressed in four of 12 tumor types." (PMID 23251904, 2012). "Previous studies have demonstrated that MTDH promotes tumor initiation and progression by modulating multiple downstream oncogenic pathways, such as NF-κB, PI3K/Akt and Wnt/β-catenin pathways." (PMID 22768080, 2012). "In recent years, MTDH, involved in aberrant proliferation, survival, and increased migration, invasiveness, and metastasis of tumor cells, has been demonstrated as a potentially crucial mediator of various types of human malignancies." (PMID 22768080, 2012). "MTDH is proposed to promote tumor progression through the integration of multiple signaling pathways including ras, myc, Wnt, PI3K/AKT, and NF-κB in various types of cancer cells, though the mechanism by which MTDH controls these signaling events is unclear." (PMID 21687633, 2011). "A recently discovered gene, metadherin (MTDH, also known as AEG-1 or LYRIC) has emerged as a potentially crucial mediator of tumor progression, metastasis, and resistance to chemotherapies." (PMID 21687633, 2011). "Statistical analysis showed a significant correlation of MTDH expression with the clinical staging of the patients, tumor classification, node classification, and metastasis classification." (PMID 22195048, 2011).
tumor (continued). "MTDH has been demonstrated to play a role in several significant stages of tumor progression, including transformation, initiation of apoptosis, invasion, metastasis, chemoresistance and angiogenesis." (PMID 21408129, 2011). "Since MTDH has been reported to inhibit tumor antigen presentation, we speculated that E2F4-induced MTDH expression contributed to the suppression of antigen presentation." (PMID 41249116, 2025). "Following 48 h of exposure, the tumor cells were analyzed for the expression of apoptosis and proliferation markers, such as Caspase-9 and Ki-67, as well as markers associated with cisplatin resistance, including APEX1, MTDH, ERK1, and STAT3." (PMID 40149331, 2025). "In support of this notion, reduced MTDH expression was observed in tumor cells with FAM114A1-KD." (PMID 41249116, 2025). "The zinc finger transcription factor Miz1 is a newly identified tumor suppressor that inhibits liver tumorigenesis, possibly by isolating oncoprotein metadherin, thus preventing metadherin from activating NF-κB, and by shifting the macrophage phenotype toward a pro-inflammatory phenotype 108." (PMID 39309440, 2024). "For example, MTDH was tightly related to advanced tumor grade and stages in patients with colorectal cancer (CRC), and could enhance CRC cell proliferation, anaerobic glycolysis and stemness via activating NF-ĸB pathway." (PMID 38625581, 2024). "In conclusion, USP7 deubiquitinated MTDH to stabilize its expression, and then contributed to CC cell proliferation, migration, invasion, and angiogenesis, as well as macrophage M2 polarization in vitro, and enhanced tumor growth in nude mice." (PMID 38625581, 2024). "Furthermore, we evaluated NF-κB and STAT3 in tumor xenograft models where MTDH remained depleted after 10 weeks." (PMID 36902125, 2023). "We also demonstrate that depletion of MTDH reduced the size of tumor spheroids, suggesting that MTDH could play an important role in their integrity, possibly affecting cell-to-cell interactions." (PMID 36902125, 2023). "There is evidence that MTDH participates in tumor angiogenesis, whereas its role in placental angiogenesis remains unclear." (PMID 37121272, 2023). "Therefore, we investigated the role of MTDH in the regulation of SUM-149 WT and sg-MTDH tumor growth." (PMID 36902125, 2023). "They showed that MTDH overexpression increased tumor growth and decreased PTX treatment efficacy." (PMID 36147518, 2022). "MTDH acting as an oncogene can promote tumor cell proliferation and inhibit apoptosis." (PMID 35875123, 2022). "On analyzing the relationship between metadherin expression and the HCC clinicopathological data, they revealed that metadherin expression was strongly correlated with the size of the tumor, histological differentiation, BCLC stage, microvascular invasion and metastasis in patients with HCC." (PMID 34577789, 2021). "Furthermore, we performed subcutaneous tumor model to verify the effect of miR-26a-5p and MTDH in PTX resistance." (PMID 34740994, 2021). "Then, we detected the expression of MTDH in xenograft tumours by IHC." (PMID 34893064, 2021). "Our result proved overexpression of circITGA7 in tumors could absorb more miR-1471, leading to a reduction of miR-1471 and miRNA-mediated attenuation of MTDH mRNA, thus suppressing invasive tumor growth." (PMID 34504842, 2021). "Similarly, the expressions of MTDH in xenograft tumours derived from KYSE30 cells with NORAD overexpression were higher than those cells with EV." (PMID 34893064, 2021). "In addition, overexpressed MTDH increased tumor size and reversed the inhibitory effect of Gem on tumor size of the model mice, and overexpressed MTDH increased tumor weight and reversed the inhibitory effect of Gem on tumor weight of the mice." (PMID 34552061, 2021). "Consequently, functional analysis showed that the tumor suppressor effect of circITGA7 was the result of regulating the miR-1471/MTDH axis." (PMID 34504842, 2021).
tumor (continued). "Moreover, Xena browser analysis indicated a higher expression of MTDH at the mRNA level in primary tumor samples compared to normal tissue (n = 1247, p-value = 7.699 × 10−9, f = 18.97)." (PMID 31979093, 2020). "Additionally, MTDH has been found to be more highly expressed in primary tumor tissues than in normal tissues." (PMID 31979093, 2020). "MiR-136-5p exerts its tumor suppressive effect by targeting the protein metadherin (MTDH)." (PMID 32074085, 2020). "Elevated MTDH expression abolished the inhibitory effect of miR-136-5p overexpression on TNBC cell proliferation, migration, and invasion (p < 0.05), suggesting that miR-136-5p exerts its tumor-suppressive function in TNBC cells by suppressing the MTDH expression." (PMID 32074085, 2020). "MTDH and IL-10 expression were observed in the cytoplasm of the tumor sections." (PMID 33003428, 2020). "Moreover, knockout of the MTDH gene significantly inhibited the growth of T-ALL xenograft tumours in nude mice." (PMID 32251289, 2020). "MTDH may serve as an anti-tumor therapeutic target that can be applied for the clinical treatment of metastatic ccRCC." (PMID 31978894, 2020). "By contrast with miR-128, MTDH was robustly increased in tumor specimens at protein level." (PMID 32993809, 2020). "We investigated whether miR-136-5p exerts its tumor-suppressive function in TNBC cells by suppressing the MTDH expression." (PMID 32074085, 2020). "Also MTDH functionally interacts with the Ha-Ras oncogene and leads to tumor development and progression in melanocytes." (PMID 31131259, 2019). "MTDH has also been reported to induce tumor cell metastasis via activating NF-κB." (PMID 30791936, 2019). "To test whether a combination effect can be observed using other GPx4 inhibitors in an MTDH-dependent manner, and to prevent tumor growth, we replaced RSL3 with ML162." (PMID 31527591, 2019). "In contrast, downregulation of MTDH could inhibit tumor cell growth, induce apoptosis, and increase the sensitivity of tumor cells to chemotherapeutic drugs." (PMID 30227879, 2018). "Our findings demonstrate that GABARAPL1 acts as a tumor promoter in TNBC partly through MTDH." (PMID 29088804, 2017). "Overexpression of MTDH can activate several downstream pathways, including the Akt pathway, the nuclear factor-κB pathway, and the Wnt/β-catenin pathway, to enhance different aspects of tumor malignancy." (PMID 27229534, 2016). "Moreover, the AED-1/MTDH siRNA-treated rats show a dramatic reduction of tumor volume at two weeks of treatment compared with untreated control rats." (PMID 26909607, 2016). "Nonetheless, the tumor cells showed lower MTDH expression than NC group." (PMID 27229534, 2016). "Mir-375 expression was significantly reduced in NPC and inhibited tumor growth by targeting MTDH." (PMID 26795575, 2016). "Collectively, accumulating evidence suggested that MTDH might participate in the tumor metastasis process and can be regarded as therapeutic target of reproduction malignancies." (PMID 27917902, 2016). "Further analysis of array-based comparative genomic hybridization (aCGH) data collected from 115 MM patients revealed that the MTDH locus is frequently amplified in these MM patient samples implying MTDH may also behave as a tumor-initiating gene in MM." (PMID 26683226, 2016). "Likewise, miR-375 was shown to be downregulated in HNSCC and to function as a tumor suppressor by regulating the expression of AEG-1/MTDH, CIP2A (cancerous inhibitor of protein phosphatase 2A)." (PMID 26504785, 2015). "Additionally, the MTDH mRNA was also higher in HCC tissues compared to their matched adjacent non-tumor tissues." (PMID 26287185, 2015). "Our results revealed that MTDH had a tumor growth-promoting effect in HCC tumors." (PMID 26287185, 2015). "Tumor suppressors miR-15a and miR-16 regulate tamoxifen sensitivity by targeting Bcl-2, miR-451 targets 14-3-3ζ, let7s target ER-α36, miR-375 targets metadherin and miR-200b/c target ZEB1." (PMID 26206152, 2015).